LYG1 (lysozyme g1)
Synonyms: SALW1939; LYGA1
Tractability: Antibody: UniProt places it where antibodies can reach, with high confidence; UniProt predicts a signal peptide or a membrane-spanning region; its Gene Ontology location is reachable by antibodies, with medium confidence.
Gene: Protein-coding gene on chromosome 2 (99,284,238 to 99,306,110, reverse strand). Ensembl gene ENSG00000144214.
Subcellular location: Secreted
Gene Ontology:
Molecular function: protein binding; lysozyme activity
Biological process: defense response to Gram-positive bacterium; peptidoglycan catabolic process
Cellular component: extracellular region
Genetic constraint (gnomAD): Loss-of-function variants: 16 observed, 22.58 expected, observed/expected ratio (o/e) 0.71, 90% interval 0.48 to 1.08. The upper end of that interval is the gene's LOEUF score, 1.08, which puts it in group 4 of 6, group 1 being the genes least tolerant of losing a copy. Missense variants: 205 observed, 248.13 expected, observed/expected ratio (o/e) 0.83, 90% interval 0.74 to 0.93. Synonymous variants: 81 observed, 92.26 expected, observed/expected ratio (o/e) 0.88, 90% interval 0.73 to 1.06.
Homologues: Orthologues: chimpanzee LYG1 (99% identical), macaque LYG1 (92% identical), dog LYG1 (81% identical), guinea pig LYG1 (76% identical), rabbit LYG1 (76% identical), rat Lyg1 (72% identical), mouse Lyg1 (71% identical), zebrafish lygl1 (33% identical), zebrafish zgc:162941 (33% identical), zebrafish lygl2 (30% identical), tropical clawed frog tmem121 (28% identical). Paralogues in human: LYG2 (41% identical).
Diseases named in the same sentence as LYG1 in open-access papers:
LYG1 is named in the same sentence as 9 diseases in open-access papers, as found by Europe PMC text mining. Sharing a sentence is not in itself a finding about the gene and the disease. The quoted sentences say what the papers report.
acute graft versus host disease (1 paper, 2025). A syndrome of immunologically mediated tissue damage that may occur following an allogeneic transplant, usually affecting the skin, liver, and GI tract. "Previous reports identified LYG1 as a regulator of T cell activation in tumor immunity and acute graft-versus-host disease (aGVHD)." (PMID 41445755, 2025).
epididymitis (1 paper, 2025). Inflammation of the epididymis. "As LYG1 is a key inflammation-associated molecule, we aimed to establish a lipopolysaccharide(LPS)-induced epididymitis model to investigate whether LYG1 participates in the pathogenesis ofepididymitis." (PMID 41445755, 2025). "To explore the role of LYG1 in oxidative stress regulation during epididymitis, we detected theactivity of SOD and the content of MDA in cauda epididymis homogenates." (PMID 41445755, 2025).
Infertility (1 paper, 2025). "Clinically, our findings imply that LYG1 deficiency may serve as a genetic predisposing factor for inflammation-induced epididymal damage and infertility." (PMID 41445755, 2025). "This study identifies LYG1-dependent pathways as potential therapeutic targets for chronic epididymitis-related infertility." (PMID 41445755, 2025). "This dissociation indicates that LYG1 primarily modulates pre-fertilization events (e.g., sperm motility, acrosomal integrity) rather than post-fertilization embryo viability, a distinction with clinical relevance for diagnosing male factor infertility." (PMID 41445755, 2025).
mood disorder (1 paper, 2017). A cognitive disorder a disturbance in which the person's mood is hypothesized to be the main underlying feature. "Therefore, LYG1 and C11orf80 are likely reliable mood disorder related genes, and may contribute to the cerebellum associated pathogenic processes in the disease development." (PMID 29225345, 2017).
ovarian carcinoma (1 paper, 2025). A malignant neoplasm originating from the surface ovarian epithelium. "The current study developed a predictive model of CSOARG for prognosis in ovarian cancer using eight key genes (WNK1, ANGPTL4, AREG, IGF1, CXCL10, GMPR, FANCB, LYG1)." (PMID 40510161, 2025).
thyroid tumor (1 paper, 2023). A benign or malignant neoplasm affecting the thyroid gland. "Our study provides evidence that OCLN, ZNF423, LYG1, and AQP5 mRNA markers can serve as reliable molecular markers for identifying NIFTP among other thyroid tumors." (PMID 37658903, 2023). "Our results suggest that OCLN, ZNF423, LYG1, and AQP5 mRNA markers might serve as reliable molecular markers for identifying NIFTP among other thyroid tumors, ultimately aiding in accurate diagnosis and management of NIFTP patients." (PMID 37658903, 2023).
tumor (3 papers, 2021 to 2025). "Furthermore, LYG1 deficiency in donor T cells preserved graft-versus-tumor response." (PMID 34262560, 2021). "The mice receiving Lyg1-/- T cells exhibited a higher survival rate, lower tumor signal and lower tumor burden than that of the mice receiving Lyg1+/+ T cells and BM cells." (PMID 34262560, 2021). "Recombinant human LYG1 protein (rhLYG1) can inhibit tumor growth by promoting the activation and IFN-γ production of tumor antigen-specific CD4+ T cells." (PMID 34262560, 2021). "While LYG1 deficiency accelerated B16 and LLC1 tumor growth due to the inhibited T cell functions." (PMID 34262560, 2021). "However, LYG1 may play a role in antitumor function by promoting the activation, proliferation, and function of CD4 + T cells in tumor microenvironment." (PMID 37658903, 2023).
LYG1 also shares sentences with these, for which no sentence is quoted: graft versus host disease (1 paper); mastocytoma (1).